ATM (ATM serine/threonine kinase)
Diseases named in the same sentence as ATM in open-access papers (continued):
Sharing a sentence is not in itself a finding about the gene and the disease.
infection (continued). "Vpr/VifIR-AA infected HeLa, THP1, or SupT cells were treated with vehicle, an ATM inhibitor (AZD1390), an ATR inhibitor (NU6027), or caffeine, and γH2AX foci were quantified 48-hours post-infection (note: these cells were not treated with a DNA damaging agent)." (PMID 37669285, 2023). "This suggested that the ATR, but not the ATM, pathway might be involved in HBV CCC DNA formation during infection." (PMID 32071277, 2020). "ATM did not impair replication of Ad9 and Ad12, which were attenuated by MRN, indicating that inhibition of viral DNA replication by MRN was unlikely to be mediated by ATM activation during these infections." (PMID 32906746, 2020). "Furthermore, although ATM is responsible for infection-induced H2AX phosphorylation, neither ATM nor the closely related ATR kinase is strictly required for efficient HSV production." (PMID 26817608, 2016). "Infection activates ATM at very early stages, without triggering cell death, followed by activation of the lysosomal system, as manifested in the high LC3 lipidation (LC3II) at a later phase of infection." (PMID 26938301, 2016). "Therefore, although ATM signaling is activated by HSV-1 infection, ATM is not vital for efficient HSV replication in HFF cells, and thus γH2AX formation is likely an incidental signal during infection." (PMID 26817608, 2016).
genetic disorder (36 papers, 2007 to 2025). "Based on the Human Gene Mutation database (HGMD) that collects germline mutations underlying or associated with human inherited diseases, 1,924 ATM variants have been described of which 756 are associated with AT." (PMID 34759960, 2021). "Briefly, radiosensitive RKO cells express mutated ATM, similarly to patients with a genetic disorder characterized by hypersensitivity to ionizing radiation." (PMID 27513864, 2016). "Ataxia Teleangiectasia (AT) is a rare genetic disease caused by biallelic mutations in the ataxia telangiectasia mutated (ATM) gene, most of which are truncations." (PMID 24405665, 2014). "Such monomers may be sequestrated in the cytoplasm by overexpressed protein ATM substrates, called “X-proteins”: we have shown that each genetic disease associated with moderate radiosensitivity and delayed RIANS was characterized by one X-protein, at least." (PMID 37443782, 2023). "Aberrations of chromosome 8, genetic disorders mainly involving T-cell leukemia/lymphoma 1 (TCL1) gene family and inactivation of ataxia-telangiectasia mutated (ATM) gene are reported to play a role in the pathogenesis of T-PLL." (PMID 40933896, 2025). "A radioprotective effect with the combination of bisphosphonates and statins, particularly with zoledronate and pravastatin (ZOPRA), was reported: the ZOPRA treatment accelerated the diffusion of the ATM monomers across the nuclear membrane in a number of genetic diseases." (PMID 37443782, 2023). "For each genetic disease, some proteins specifically overexpressed in the cytoplasm and interacting with the ATM protein may sequester the ATM monomers in the cytoplasm and prevent their diffusion in the nucleus and the phosphorylation of H2AX histones at the DSB sites." (PMID 37626928, 2023).
neurodegenerative disease (32 papers, 2014 to 2025). A disorder of the central nervous system characterized by gradual and progressive loss of neural tissue and neurologic function. "Declining ATM levels with age and deficits in ATM signaling are associated with the development of neurodegenerative diseases." (PMID 36613733, 2022). "A‐T is an autosomal recessive childhood neurodegenerative disease that is caused by biallelic mutation of ATM, leading to absence or deficiency of ATM protein or kinase function." (PMID 29845714, 2018). "Neurodegenerative diseases can arise from defective repair of Top1cc (SCAN1 caused by TDP1 deficiency) as well as from defective response to DSBs (AT caused by ATM deficiency)." (PMID 26578593, 2016). "This may suggest that the ATM mutation is accelerating the aging phenotype of microglia in A-T, contributing to an accelerated neurodegenerative disease process." (PMID 40959764, 2025). "Indeed, developing neurons are known to be exquisitely sensitive to DNA damage-induced apoptosis as mutations in critical mediators of the DDR, like ATM, cause neurodegenerative diseases." (PMID 24516599, 2014). "In addition, flies with mutations in ATM, a gene associated with the neurodegenerative disease ataxia-telangiectasia (A-T) in humans, show elevated levels of AMPs in glial cells demonstrating that Relish is involved in the development of the degenerative disease pathology." (PMID 31481676, 2019). "Persistent ATM activation has been observed in mouse models of PD and other neurodegenerative diseases, exacerbating neuronal damage." (PMID 40723779, 2025). "Persistent activation of ATM signaling has been demonstrated in mouse models of both PD and other neurodegenerative diseases, while targeted inhibition of ATM activity has neuroprotective effects." (PMID 37047285, 2023). "The serine/threonine kinase ATM is critical for DDR and its deficiency leads to the hereditary ataxia telangiectasia (AT) syndrome, which is primarily a neurodegenerative disease." (PMID 26578593, 2016). "ATM activation, while protective in the short term and plays a protective role under physiological conditions, can become maladaptive if sustained, contributing to excessive genomic instability, neuronal dysfunction, and cell death, especially in the context of neurodegenerative diseases." (PMID 40723779, 2025). "Moreover, although it is well established that ATM or ATR mutations may lead to genomic instability, thereby promoting tumorigenesis, patients with ATM or ATR mutations are also reported to have neurodegenerative diseases." (PMID 38554113, 2024). "Therefore, better understanding of the ATM-AKT-GSK3β-αNAC/γTX signaling axis may provide new insights into the pathogenesis of neurodegenerative diseases and ER- stress-related human diseases, and could be valuable in evolving novel treatment strategies." (PMID 32665601, 2020).
adenocarcinoma (17 papers, 2012 to 2025). A common cancer characterized by the presence of malignant glandular cells. "KRAS, ARID1A, ABL1, ATM, RET, and CDH1 mutations have been detected in the mesonephric adenocarcinomas containing sex cord-like pattern; among these genes, KRAS mutation was the most frequent." (PMID 31739799, 2019).
hematological malignancies (16 papers, 2012 to 2025). "Although ATM mutations drive hematologic malignancies, ATM mutations occur in less than 1% patients with AML and MDS." (PMID 41457124, 2025). "Of note, overlap phenotypes of both hematologic and non-hematologic malignancies were documented in 3 patients with ATM mutations." (PMID 36765721, 2023). "As a result, such an ATM gene variation may determine an individual's susceptibility to BTEX‐induced blood disorders." (PMID 35235704, 2022). "However, the physiologic basis of 11q deletions and dysfunction of the ATM gene in the tumorigenesis of hematological malignancies remained unclear." (PMID 36635772, 2023). "In a few hematological malignancies, ATM-deficiency was shown to confer sensitivity to PARP inhibitors, indicating that ATM might be included in the DDR factors whose mutation or loss of expression confer sensitivity to this class of drugs." (PMID 24252502, 2013).
neurological disorders (14 papers, 2018 to 2026). "In A-T, antisense oligonucleotide treatment has shown amelioration of neurological disease progression in patients with selected ATM mutations." (PMID 38933494, 2024). "It codes for a protein of the same name ATM, and in recent years there has been growing evidence that ATM plays a role in a variety of neurological diseases." (PMID 34421351, 2021). "A better understanding of the molecular pathways affected by ATM may enable the discovery of new treatments or therapies to slow or stop the progression of this debilitating neurological disorder." (PMID 37296624, 2023). "Thus, reduced lamin A levels due to non-functional ATM could explain the neurological disorders and premature ageing characteristic of this disease." (PMID 35721517, 2022).
prostate (9 papers, 2012 to 2024). "ATM is considered one of the DNA damage repair genes, and its activation can be seen in the earlier stages of prostate tumorigenesis." (PMID 33632199, 2021). "ATM mutations could alter the DNA damage response (DDR) machinery leading to genomic instability and acquisition of subsequent mutations that could affect prostate carcinogenesis." (PMID 35347810, 2022). "Our findings demonstrate that ATM/ATR inactivation is a crucial step in promoting androgen-induced genomic instability and prostate carcinogenesis." (PMID 23272087, 2012). "In order to elucidate the effects of ATM inhibition on injured proximal tubular epithelia, we administered KU55933 to mice with cisplatin-induced kidney injury and analyzed FACS-isolated proximal tubular epithelia, which were exclusively labeled by cre recombinase-mediated reporter expression." (PMID 32157166, 2020).
hematological cancers (8 papers, 2015 to 2025). "ATM inactivation is a common event in hematological cancers, often coinciding with the loss of a section of the 11q chromosomal arm." (PMID 38347838, 2024). "Especially our finding highlighted mutations in ATM genes were associated with a high level of mortality and presentation of both hematologic and non-hematologic cancers in children and young-adult IEI patients." (PMID 36765721, 2023). "We identified recurrent highly pathogenic variants affecting important drivers of hematological cancer (ATM), epigenetic regulators (ISX and SETDB1), and mediators of DNA replication (POLQ)." (PMID 33809641, 2021). "Surprisingly all deceased patients from non-hematologic malignancy were ATM-deficient patients (n = 4, 100%) including all 3 cases with overlapping hematologic cancers." (PMID 36765721, 2023). "The age at the time of death in these 3 patients was not significantly different from other ATM-deficient patients with only- hematologic cancers (13.5 (IQR 8.6–19.5) vs. 14.7 (IQR 10.0–21.5) years, p = 0.62)." (PMID 36765721, 2023). "These preclinical results demonstrate the therapeutic potential of targeting POLΘ in oncogene-driven hematologic cancers, especially in MCL, where cyclin D1 overexpression is ubiquitous and ATM deficiency is common, but may extend to other oncogene-driven hematologic cancers." (PMID 40608419, 2025).
cardiovascular disease (6 papers, 2014 to 2024). "Together, these studies provide evidence for the relationship between ATM and metabolic aberrations linked to cardiovascular disease." (PMID 29152614, 2017). "ATM deficiency is suggested to increase the risk of dying from cardiovascular disease." (PMID 29152614, 2017). "Thus, the increase of NOX-2 derived ROS formation may shed new light in the putative relationship between mutation of the ATM gene and risk of cardiovascular disease." (PMID 39326070, 2024). "In the present study, we found that prebiotic/probiotic supplementation reduced ARG1 (30 days), ATM (90 days), and CD80 (60 days), which may translate to a reduced cardiovascular disease risk." (PMID 36437471, 2022). "Collectively, these studies suggest that ATM may be essential in maintaining redox and mitochondrial homeostasis that can ultimately protect against cardiovascular disease." (PMID 29152614, 2017). "Additionally, the DDR protein ATM plays a poorly defined role in cardiovascular disease, with individuals and mice with only one functional ATM gene showing elevated cardiovascular disease, while a high fat diet suppresses ATM protein expression in wild-type animals." (PMID 34829691, 2021).
blood cancer (5 papers, 2016 to 2025). "Studying mice that were engineered to have an inactive version of ATM in their blood cells showed that such mice developed blood cancers faster than mice have no ATM in their blood cells." (PMID 27304073, 2016).
metabolic disease (4 papers, 2016 to 2024). A congenital disorder (due to inherited enzyme abnormality) or acquired (due to failure of a metabolically important organ) disorder resulting from an abnormal metabolic process. "Hence, the reduction of FMD in our ATM cohort cannot be attributed to a coexistent metabolic disease affecting arterial dysfunction, that, thereby, must be explained by an alternative mechanism." (PMID 39326070, 2024). "Moreover, it is recognized that deficiency in DNA repair machinery such as ATM, WRN, and Ercc1, accelerates aging and causes severe metabolic disorders." (PMID 29717979, 2018).
bacterial infection (3 papers, 2010 to 2022). "Thus, tonic ATM activation at homeostasis suppresses MCSF-induced type I IFNs and type I IFNs induced by bacterial infection are required for DDR activation via ATM and DNA-PKcs." (PMID 35330617, 2022). "Bacterial infection of BMDM with L. monocytogenes leads to dsDNA breaks, which activates ATM and DNA-PKcs." (PMID 35330617, 2022).
colon (2 papers, 2012 to 2017). "However, there was a tendency towards ATM negativity in colon NETs and G2 NETs when compared with rectal NETs and G1 NETS, respectively, although statistical significance was not reached (p>0.05)." (PMID 22485171, 2012).
heart disease (2 papers, 2012 to 2023). "ATM gene was shown to also decrease life expectancy in oncologic patients with heart disease." (PMID 38203612, 2023).
movement disorder (2 papers, 2022 to 2024). Neurological conditions resulting in abnormal voluntary or involuntary movement, which may impact the speed, fluency, quality and ease of movement. "As only one ATM variant was found in the patient, this will not be the sole cause of the progressive movement disorder." (PMID 39180521, 2024). "Inhibited pathways (shown in blue) controlled apoptosis, inflammation of the organs, movement disorders, motor dysfunction, PI3K/AKT, ATM, and PTEN." (PMID 35743705, 2022).
neurodevelopmental disorder (2 papers, 2023 to 2024). A behavioral and cognitive disorder with onset during the developmental period that involves impaired or aberrant development of intellectual, motor, or social functions.
CNS tumor (1 paper, 2025). "In summary, germline P/LP variants in CPGs are enriched in the PBTA CNS tumor cohort, with a novel potential association between ATM P/LP variants and PB." (PMID 39974082, 2025).
inflammation (1 paper, 2022). Aberrant reaction of the microcirculation characterized by movement of fluid and leukocytes from the blood into extravascular tissues. "A high bronchoalveolar sensitivity to ROS-induced DNA damage has been documented in Atm-deficient mouse model, supporting the hypothesis that ATM plays a pivotal role in the control of oxidative stress-driven lung inflammation and fibrosis." (PMID 35257272, 2022).
mitochondrial disease (1 paper, 2022). "ATM absence, indeed, led to increased mitochondrial ROS, reduced mitochondrial functions, and decreased mitophagy, leading to the conclusion that AT disease should be considered also as a mitochondrial disease." (PMID 36422718, 2022).
muscular disorders (1 paper, 2025). "Thus, given the key role of Ca2+ in muscle physiology, and considering that alterations of Ca2+ homoeostasis are responsible in many muscular disorders, investigating the ATM role in calcium signalling could increase the knowledge on A-T pathophysiology." (PMID 40234386, 2025).
psychiatric disorder (1 paper, 2022). A disorder characterized by behavioral and/or psychological abnormalities, often accompanied by physical symptoms. "Our data display how ATM affects both inhibitory and excitatory neurotransmission, extending its role to a variety of neurological and psychiatric disorders." (PMID 35842432, 2022). "Data here presented indicate how ATM affects excitatory neurotransmission extending the role of ATM to a much wider spectrum of neurological and psychiatric disorders." (PMID 35842432, 2022).
ATM also shares sentences with these, for which no sentence is quoted: cerebellar ataxia (14 papers); progressive ataxia (8); hereditary breast and ovarian cancer syndrome (7); multiple myeloma (7); autosomal recessive disease (5); Peutz-Jeghers syndrome (5); prostate adenocarcinoma (5); xeroderma pigmentosum (5); Bloom syndrome (4); diffuse non-Hodgkin’s lymphoma (4); Splenomegaly (4); Cockayne syndrome (3); combined immunodeficiency (3); DNA repair disorder (3); epithelial ovarian tumor (3); Friedreich ataxia (3); hereditary Non‐Polyposis Colorectal Cancer (3); Hypercholesterolemia (3); inflammatory bowel disease (3); intrahepatic cholangiocarcinoma (3); Oculomotor apraxia (3); papillary thyroid carcinoma (3); alopecia (2); Alpha-thalassemia (2); amyotrophic lateral sclerosis (2); anaplastic thyroid cancer (2); autosomal recessive cerebellar ataxia (2); breast ductal carcinoma in situ (2); bronchiectasis (2); cardiomyopathy (2).
A further 234 diseases each share a sentence with ATM in 2 papers or fewer.